INS (insulin)
Diseases named in the same sentence as INS in open-access papers (continued):
Sharing a sentence is not in itself a finding about the gene and the disease.
diabetes (continued). "Insulin therapy regimens for people with type 1 diabetes (PWT1D) should mimic the physiological insulin secretion that occurs in individuals without diabetes." (PMID 36510287, 2022). "In people with T1DM, 16 cancer cases were diagnosed; in people with T2DM, 1689 new cancer cases were diagnosed during follow-up (180 in insulin users, 121 of whom were insulin-only users), while 12,882 cancers were diagnosed in people without diabetes." (PMID 35681699, 2022). "All mothers involved in this study did not develop any obvious symptoms related to diabetes throughout pregnancy, even diabetes requiring insulin therapy or any clinical symptoms of insulin resistance, like acanthosis nigricans." (PMID 35656378, 2022). "Blocking IDE activity may be beneficial for the maintenance of high circulating insulin levels and other substrates of IDE in pathological conditions such as diabetes." (PMID 35350789, 2022). "LADA patients must have at least one diabetes-mellitus autoantibody (DMab), debut at an age over 30, and have no need for insulin treatment during the first 6 months after diagnosis." (PMID 36429105, 2022). "While insulin therapy normalized the blood glucose levels in the diabetic mice, it did not rescue the diabetes-induced suppression of Cyp2r1." (PMID 35524739, 2022). "According to a report, people with type 2 diabetes mellitus (T2DM) with DN are more insulin-resistant than those without." (PMID 36111327, 2022). "She had a history of hypertension, diabetes mellitus not requiring insulin, and atrial fibrillation for which she was on anticoagulant therapy." (PMID 36168361, 2022). "In this clinical trial, we sought to determine whether adding exenatide to basal insulin therapy in early T2DM can enhance the achievability of beta-cell functional recovery and diabetes remission, as compared to basal/bolus therapy and basal insulin alone." (PMID 36244997, 2022). "Higher insulin doses can increase the risk of hypoglycaemia when exercise begins because exogenous insulin in a person with T1DM remains active at a time when people without diabetes would experience a drop in circulating insulin." (PMID 36425473, 2022). "During insulin secretion and synthesis, the transcription factor Glut2, which controls transport, and the transcription factors Pdx1, MafA and NeuroD, which control synthesis, are regulated by lncRNA TUG1, and interference with lncRNA TUG1 leads to diabetes." (PMID 36225311, 2022). "As the 4 patients had no other discomfort other than patient A who had diabetes, patient A was placed on therapy comprising the insulin pump, acarbose, and platelet booster capsule." (PMID 36401425, 2022). "Many studies have also disclosed poorer outcomes among insulin-treated compared to non-insulin treated patients with diabetes after MI or PCI but have not specifically examined patients with type 1 diabetes." (PMID 36068573, 2022). "Therefore, under pathological conditions of hypoinsulinemia in diabetes, antibodies inhibiting the secreted form of IDE should increase insulin levels and ameliorate pathological features of the disease." (PMID 35350789, 2022). "NOD mice in which BCR reactivity is biased toward insulin or neural antigen peripherin develop diabetes at an earlier age than non-transgenic counterparts." (PMID 36275764, 2022). "MiR‐199a‐5p is up‐regulated in diabetes, and in vitro studies have shown that miR‐199a‐5p targets and represses GLUT4, a glucose transporter isoform that increases glucose transport in response to insulin." (PMID 34984856, 2022). "Many studies have defined MH as the absence of MetSyn, insulin sensitivity, absence of hypertension, diabetes, hyperlipidemia, or any of these metabolic factors." (PMID 35566567, 2022). "During exercise, circulating insulin stimulates muscle glucose uptake such that in individuals without diabetes, insulin typically decreases and glucagon and other counterregulatory hormones rise." (PMID 36992764, 2022).
diabetes (continued). "T2D is the most common type of diabetes and occurs when your pancreas does not produce enough insulin and cells become resistant to insulin, leading to lower cellular uptake of glucose and therefore higher blood glucose levels." (PMID 35992116, 2022). "Diabetes is a serious, chronic illness that occurs when the pancreas fails to produce enough insulin (a hormone that regulates blood sugar, or glucose) or when the body is unable to use the insulin that is produced efficiently." (PMID 35737691, 2022). "The associations were exacerbated by insulin treatment during GDM pregnancy in women with and without subsequent diabetes mellitus." (PMID 36085031, 2022). "Diabetes occurs when the pancreas can no longer create insulin or when the body is not able to make proper use of it." (PMID 36555184, 2022). "As demonstrated in a recent meta-analysis, SGLT-2i treatment is associated with increased plasma fasting glucagon levels in patients with diabetes compared with non-SGLT-2i treatments with a reduction of insulin and increased ketone body levels." (PMID 35265043, 2022). "From the group reporting taking insulin to participants without diabetes, protein foods and vegetables exhibited a decreasing trend in percentage of energy contribution, while beverages, water, and other showed an increasing trend." (PMID 36014790, 2022). "Whereas, in diabetes mellitus type 1 there is an absolute lack of insulin because of breakdown of islet cells in the pancreas." (PMID 36584077, 2022). "Insulin administration does not appear to influence mortality in infected patients suffering from diabetes." (PMID 36406478, 2022). "Our results show that TRE did not improve peripheral and hepatic insulin sensitivity, skeletal muscle mitochondrial function, energy metabolism or hepatic lipid content, all of which are known to be affected in type 2 diabetes mellitus." (PMID 35871650, 2022). "There were 632 (36.3%) patients with diabetes, which were under diet control alone (12.8%), oral antidiabetic drugs (74.7%), or insulin-based therapy (12.5%), and 1110 (63.7%) patients without diabetes." (PMID 35386265, 2022). "None of the patients without diabetes and 22.2% of diabetes patients received an additional insulin injection during IDPN infusion." (PMID 35296793, 2022). "Participants did not follow postoperative diabetes recommendations because of lack of skills to manage and titrate insulin, even when recommendations were specific about dosages and regimens (Skills)." (PMID 35101113, 2022). "Type 2 diabetes (T2D) is a form of diabetes generally characterized as elevated blood glucose levels, insulin resistance and relative lack of insulin." (PMID 35064189, 2022). "Diabetes mellitus (diabetes) is a metabolic disorder in which the body becomes resistant to the effect of insulin or does not produce enough of this hormone to process glucose." (PMID 35236427, 2022). "At present, there is still no good way to cure diabetes, and the periodical monitoring of glucose concentrations and subcutaneous injections of human insulin remain the main method of controlling insulin-dependent diabetic patients in clinics." (PMID 36080102, 2022). "Type 2 diabetes mellitus is a metabolic disorder in which the body does not produce enough insulin or does not respond to it correctly." (PMID 35237285, 2022). "In this systematic literature review, we identified studies using surrogate markers of insulin sensitivity and secretion and its correlation with gold standards in a population without diabetes using dietary interventions." (PMID 35631177, 2022). "The people with diabetes were discharged without a way to cover insulin costs and were fearful they would be readmitted to the hospital." (PMID 35436214, 2022). "None of the patients needed more than 25 units of insulin per day, regardless of the presence of diabetes prior to admission." (PMID 34168292, 2022).
diabetes (continued). "A recent study reported that WSCD2 expression in human islet was positively correlated with insulin secretion and negatively correlated with HbA1c, suggesting possible hypermethylation in the WSCD2 gene in islet cells in diabetes status and a role of WSCD2 in glucose metabolism." (PMID 35721735, 2022). "Four types of diabetes are known: type 1 T1DM (insulin-dependent); type 2 (non-insulin-dependent); gestational diabetes; and a condition known as prediabetes." (PMID 35600869, 2022). "Among them, DULA is currently included in the drug list of the national medical insurance and reimbursed only in patients with a BMI >25 kg/m2 whose diabetes is not controlled by metformin or insulin." (PMID 35250578, 2022). "One interpretation of this finding is that any beneficial effects of alcohol intake on insulin sensitivity will not be enough to prevent progression to diabetes in individuals with more pronounced autoimmune -induced insulin deficiency." (PMID 35846274, 2022). "In this study, various diabetes indices were obtained through OGTT and serum insulin level tests." (PMID 35831319, 2022). "In the present study, we only included people without diabetes to avoid the effect of oral hypoglycemic drugs and exogenous insulin." (PMID 35755073, 2022). "In the 8-week-old db/db mice and the 12-week-old db/+ control mice, rhMG53-WT had no influence on their insulin sensitivity, highlighting that the detrimental effect of rhMG53-WT is dependent on the progression of diabetes." (PMID 36337049, 2022). "Nevertheless, intranasal insulin administration from 8 to 16 weeks of diabetes provided no additional effects on DPN compared with simple RAGE deletion in STZ-induced diabetic RN mice." (PMID 36477360, 2022). "In Korean men and women, with and without diabetes, HOMA-IR and fasting insulin levels were found to be inversely associated with composite indices of femoral neck strength." (PMID 36233562, 2022). "Therefore, while insulin therapy continues to remain the core of the therapeutic approach in diabetes, ACC dysregulation due to glycemic stress or unwanted side effects of insulin abundance should be resolved for optimal outcomes." (PMID 36295842, 2022). "Human studies indicate that intranasal insulin enhances cognitive performance irrespective of concurrent diabetes." (PMID 36244663, 2022). "Notably, patients with obesity and patients with obesity and diabetes showed significantly higher BMI, WHR, fasting insulin, hsCRP and leptin and significantly lower HDL-cholesterol and adiponectin levels than Control subjects." (PMID 35585213, 2022). "Hepatic insulin resistance and even whole-body insulin are universally observed in MAFLD patients with T2DM, and it may explain the reason for more LVDD occurring in MAFLD patients with diabetes." (PMID 35928895, 2022). "I hope there will be better days, when kids with diabetes do not feel like outliers and can take their insulin without having to hide it." (PMID 35008043, 2022). "The relationship between dyslipidemia and diabetes may be as follows: LDL cholesterol decreases the expression of cyclin B1 in pancreatic β-cells and inhibits insulin secretion mediated by the LDL receptor, resulting in insulin resistance." (PMID 35992095, 2022). "Post-randomization diabetes-related adverse event or the use of antihyperglycaemic medication (insulin or oral treatment) recorded on at least one follow-up visit form for a person without evidence of diabetes mellitus at baseline." (PMID 35441656, 2022). "The second-phase insulin and CP strongly correlate with AUC (I0-30)/AUC (G0-30), AUC (I0-120)/AUC (G0-120), I30, I30/G30, BIGTT-AIR0-30-120 in NGT and with I0/G0, AUC (I0-30)/AUC (G0-30), BIGTT-AIR0-30-120, I30/G30, first-phase Stumvoll in pre-diabetes." (PMID 36100292, 2022).
diabetes (continued). "Future research is needed to elucidate the specific mechanisms of the link between CETP inhibition and incident diabetes, including the impact of CETP inhibition on cholesterol efflux from beta-cells, induction of insulin synthesis by beta cells, and increased glucose uptake by muscle." (PMID 35441656, 2022). "The link between insulin and cancer is the topic of this review, but we recognize the high likelihood that insulin is not the only link between obesity, diabetes, and cancer." (PMID 35244142, 2022). "Therefore, we decided to investigate the possible effects of NMES on diabetes control factors such as FBS, total daily dose of insulin and HbA1c in children and adolescents with T1DM who were aged seven to 18 years old." (PMID 36221091, 2022). "The lack of access to affordable insulin remains a key barrier for successful treatment of diabetes and results in further complications and premature deaths." (PMID 36292966, 2022). "In the case of diabetes, exogenous insulin does not adapt in a physiological manner once it has been administered, which can lead to hypoglycaemia." (PMID 35577814, 2022). "Like berberine, numerous phytonutrients exert anti-obesity and anti-diabetes effects independent of the insulin signaling pathway." (PMID 36145160, 2022). "At present, the treatment of type 1 diabetes mellitus is still insulin, but the long-term treatment effect of intensive insulin therapy is not ideal." (PMID 36583004, 2022). "The metabolic risk in AD is further supported by findings indicating defects in the insulin signaling pathway irrespective of diabetes." (PMID 35453527, 2022). "In 2001, Wilkin T.J. published a theory that the divergence between an insulin-dependent (type 1) and a non-insulin-dependent diabetes mellitus (type 2) blurs and considers overlay rather than overlap of these two types." (PMID 35784568, 2022). "Moreover, the impact of incretin hormones such as GLP1 and GIP on both insulin secretion and satiety has been widely reported, with GLP1-agonists now being regularly employed in the treatment of type 2 diabetes mellitus." (PMID 36281448, 2022). "Moreover, the insulin secretory capacity of our LADA patients was nearly three times as their T1DM patients, we here broaden the application of DFF in diabetes classification." (PMID 36204110, 2022). "Diabetes is a chronic disease that occurs when the body cannot use blood sugar (glucose) properly because the body does not make sufficient insulin; therefore, insulin must be injected regularly every day to stay alive." (PMID 36140119, 2022). "The AE profile of TEP appears to be acceptable, but deterioration of glucose control in patients with diabetes or prediabetes, at times requiring insulin therapy, was noted in 10% of patients." (PMID 36479875, 2022). "Since fructose does not react with insulin in the human body, it is frequently included in the diets of people with diabetes." (PMID 36613324, 2022). "Evidence from studies depicted its clinical significance in diabetes patients as it affects glucose tolerance through different mechanisms and regulates glucose metabolism by lowering insulin sensitivity, not by affecting β-cell function." (PMID 35178205, 2022). "Men more often presented with arterial hypertension, coronary artery disease without infarction, myocardial infarction, hyperuricemia, diabetes with or without insulin therapy, alcoholism, peripheral artery disease, or anemia." (PMID 35610473, 2022). "From the group reporting taking insulin to those with T2D but not using insulin to participants without diabetes, grains exhibited a decreasing trend in consumption frequency and energy contribution, while alcohol showed an increasing trend." (PMID 36014790, 2022). "Type 2 Diabetes Mellitus (T2DM) is a metabolic disorder in which insulin secretion is impaired by pancreatic cells and the inability of insulin-sensitive tissues to respond to insulin." (PMID 36441733, 2022).
diabetes (continued). "The effects of caffeine alone on insulin sensitivity and glycemic control in people with diabetes and healthy controls are negative or controversial." (PMID 36632095, 2022). "Many people with diabetes are forced to ration or go without insulin, and they turn to crowdfunding websites to seek financial donations to purchase insulin needed to reduce health risks and mortality, and sustain quality of life." (PMID 35436214, 2022). "Diabetes mellitus is a chronic, non-communicable disease that occurs when the pancreas does not produce enough insulin or cannot use the insulin effectively." (PMID 35628010, 2022). "Diabetes patients with CRD used less fast-acting (10.0% vs. 12.4%, 2018, p <.0001), less long-acting (25.2% vs. 29.8%, 2018, p <.0001), more premixed (59.9% vs. 53.8%, 2018, p <.0001), and more intermediated-acting insulin (12.7% vs. 12.3%, 2018, p = .0061)." (PMID 36093107, 2022). "There is a strong and pressing need for new technologies, such as automated insulin delivery (AID) systems, which may reduce the behavioral burden of diabetes self-management while improving health outcomes." (PMID 35853530, 2022). "As an example, one study found that 17% of patients with diabetes were considered non-adherent to their medications, and this increased with the presence of insulin prescriptions and obesity." (PMID 36005937, 2022). "While the glucose to insulin ratio provides potentially useful indication of insulin sensitivity in the absence of diabetes, this measure loses utility with elevated fasting glucose." (PMID 35634390, 2022). "Type 2 diabetes mellitus is a metabolic disorder that is characterized by high blood sugar (hyperglycemia) in the context of insulin resistance and relative lack of insulin." (PMID 36584077, 2022). "Insulin resistance and impaired insulin secretion have been described in individuals without diabetes history who recovered from SARS-CoV-2 infections." (PMID 35292829, 2022). "Metformin, insulin secretagogues, glycosidase inhibitors, glucagon-like peptide-1 (GLP-1), analogs, DPP-4 inhibitors, SGLT-2 inhibitors, as well as insulin and its agonists are used to treat diabetes." (PMID 35845787, 2022). "Qualitative studies have shown the dramatic positive impact that a diagnosis can have on quality of life; patients that have discontinued insulin treatment after many years describe feeling like they no longer have diabetes." (PMID 35445424, 2022). "Using modern diabetes technologies (like personal insulin pumps and continuous glucose monitoring) helps to minimize the deteriorating effect of JIA exacerbations and the rheumatoid treatment on metabolic control of diabetes." (PMID 34999914, 2022). "Despite not being recommended, insulin is still commonly prescribed as the first injectable therapy prior to GLP-1 RAs for inadequately controlled diabetes in real-world practice owing to its cost-effectiveness." (PMID 36559020, 2022). "Interestingly, NSD2 has been demonstrated to be downregulated in patients with type 2 diabetes mellitus, and NSD2 upregulation promoted the proliferation of pancreatic β cells and increased insulin secretion, leading to reduced glucose concentration." (PMID 35354439, 2022). "Prevalence of diabetes was lower in our cohort, and we did not record insulin therapy or hemodialysis, whereas age, gender, and hypercholesterolemia showed similar numbers." (PMID 35956221, 2022). "Insulin is also a famous therapeutic peptide for diabetes mellitus; it is widely used for subcutaneous injection rather than NPs, as it has been extremely difficult to develop an oral form of insulin." (PMID 35741380, 2022). "Patients without diabetes mellitus, which is a strong risk factor for coronary artery disease mortality, may have been discharged from the hospital in a shorter period of time, because they did not need additional coordination of oral hypoglycemic drug, insulin, nor patient education." (PMID 35208570, 2022).